Y_RNA (Y RNA )
Gene: Miscellaneous RNA gene on chromosome 12 (33,982,465 to 33,982,566, reverse strand). Ensembl gene ENSG00000201624.
Homologues: Orthologues: chimpanzee Y_RNA (100% identical), macaque Y_RNA (91% identical). Paralogues in human: Y_RNA (91% identical), Y_RNA (88% identical), Y_RNA (87% identical), Y_RNA (86% identical), RNY3 (85% identical), RNY3P1 (85% identical), Y_RNA (85% identical), Y_RNA (84% identical), Y_RNA (83% identical), Y_RNA (82% identical), RNY3P11 (81% identical), Y_RNA (81% identical), and 98 more.